AHR (aryl hydrocarbon receptor)
Diseases named in the same sentence as AHR in open-access papers (continued):
Sharing a sentence is not in itself a finding about the gene and the disease.
Alzheimer disease (27 papers, 2016 to 2026). A progressive, neurodegenerative disease characterized by loss of function and death of nerve cells in several areas of the brain leading to loss of cognitive function such as memory and language. "AhR is associated with Alzheimer’s disease too, which is a neurodegenerative illness featuring aggregation of β-amyloid plaques, which cause neuroinflammation and promote neuronal loss." (PMID 35743162, 2022). "Alzheimer’s disease (AD), a neurodegenerative disease characterized by the aggregation of amyloid beta (Aβ) plaques that induce neuroinflammation and promote neuronal loss, has been linked with AhR." (PMID 34685709, 2021). "Exposure to the xenobiotic and AhR ligand benzo[a]pyrene, which directly binds to the AhR and causes its nuclear localization, shortens the lifespan in mice, and promotes neurodegeneration as well as Alzheimer’s disease and Parkinson’s disease-like phenotypes in zebrafish." (PMID 32009975, 2019). "Dysregulation of the association between tryptamine levels, AHR signalling pathway activation, and MAO activity is observed in Alzheimer’s disease (AD), Parkinson’s disease (PD), autism spectrum disorder (ASD) and schizophrenia." (PMID 39812050, 2025). "Most recently patients with Alzheimer’s disease have been reported to have increased circulating levels of I.S. and disruption of AhR signaling, giving further evidence for the role of I.S. in contributing to cognitive dysfunction." (PMID 37569342, 2023). "In a mouse model of Alzheimer’s disease, AhR activation alleviates cognitive deficits through the upregulation of neprilysin: the main endogenous enzyme of β-amyloid catabolism." (PMID 35743162, 2022). "At the same time, only the IDO1-kynurenine-AhR cascade has been clearly shown to be involved in the development of Alzheimer’s disease." (PMID 35743162, 2022). "While AHR agonists exert protective effects in Alzheimer’s disease (AD) models, their relevance in humans remains unclear." (PMID 41652618, 2026). "AhR reduces proinflammatory cytokine expression in astrocytes and microglia and affects the development of neurological diseases such as Parkinson’s disease (PD), multiple sclerosis (MS), Alzheimer’s disease (AD), and epilepsy." (PMID 37521424, 2023). "The hypothesis that AhR is involved in the neurodegenerative processes in Parkinson’s disease and Alzheimer’s disease derives from both human and in vitro studies." (PMID 35743162, 2022). "These authors also found the AhR to be increased in the serum of Alzheimer’s disease patients." (PMID 32867244, 2020). "As SARS-CoV-2 severity is predominately evident in the elderly, it is notable that recent data shows the AhR to be increased in the brain with age, being further increased in the brains of Alzheimer’s disease patients, indicating a role for heightened AhR levels in the ageing process." (PMID 32867244, 2020). "Likewise, neuroprotective activities of clozapine as shown in the Tg-APPswe/PS1dE9 mouse model of Alzheimer’s disease might also be related to increased AhR signaling." (PMID 34979820, 2022). "IPA-induced aryl hydrocarbon receptor (AhR) activation inhibited neuroinflammation in APP/PS1 mice, a mouse model of Alzheimer’s disease (AD)." (PMID 36079724, 2022). "Interestingly, prototype AhR activators, such as TCDD and BaP, were shown to contribute to the development and progression of age-associated diseases in different model systems and a recent study showed increased AhR levels in serum brains of Alzheimer’s disease patients." (PMID 33349622, 2020). "However, there is no information concerning the behavior and participation of AHR in the human aging brain or in Alzheimer’s disease (AD)." (PMID 32183254, 2020).
triple-negative breast carcinoma (27 papers, 2013 to 2026). An invasive breast carcinoma which is negative for expression of estrogen receptor (ER), progesterone receptor (PR), and human epidermal growth factor receptor 2 (HER2). "In both triple-negative breast cancer and inflammatory breast cancer cell lines, AhR activation via 6-formylindolo(3,2-b)carbazole (FICZ), a prototypical AhR ligand, increased expression of the EMT-associated genes Snail1, Twist, and vimentin." (PMID 38339226, 2024). "This highlights the complexity of AhR functions in triple-negative breast cancer and necessitate further work to understand these differences." (PMID 38807762, 2024). "In triple-negative breast cancer, AhR activation led to upregulation of stem-related gene expression." (PMID 38339226, 2024). "TDO2 is expressed in tumor cells that produce sufficient intracellular kynurenine concentrations to chronically activate the AhR, and by pro-inflammatory cytokines such as IL-6 in triple-negative breast cancer." (PMID 35203450, 2022). "Here, we provide evidence supporting that AHR is a CMA client protein which undergoes lysosomal degradation in triple-negative breast cancer (TNBC) cells." (PMID 33562118, 2021). "Among the most promising molecules, ITE, an endogenous AhR agonist, reduces the aggressiveness of triple-negative breast cancer (TNBC) by downregulating JAG1-NOTCH1 signaling." (PMID 33451095, 2021). "Here, we report that AHR undergoes chaperone-mediated autophagy in MDA-MB-468 triple-negative breast cancer cells." (PMID 33562118, 2021). "Genistein can confer sensitivity to triple-negative breast cancer for antiestrogen therapy by preventing and reversing AhR-dependent BRCA1 hypermethylation." (PMID 32085612, 2020). "Our laboratory demonstrated that AHR inhibitors or AHR knockout slows triple negative breast cancer and oral squamous carcinoma cell migration." (PMID 33396563, 2020). "Similar results were obtained in triple negative breast cancers cells, in which migration and anchorage-independent growth was diminished after AHR knockdown." (PMID 33396563, 2020). "Taken together, our results show that YL-109 suppresses cell growth through AhR signaling in both ER-positive and triple-negative breast cancer cells." (PMID 25403352, 2014). "DATS may inhibit growth and migration in these premalignant cells in a similar fashion as observed in a study using a newly identified AhR agonist, Flavipin, in triple-negative breast cancer cells." (PMID 38255999, 2024). "Similarly, CM from Py8119 cells, another triple-negative breast cancer cell line, also enhanced AHR expression and activity." (PMID 39690159, 2024). "Inadvertent AhR activation by chemotherapy, resulting in suppression of innate immunity responses (i.e interferon type I production) has been recently reported also in triple negative breast cancer." (PMID 38807762, 2024). "Higher basal AHR expression in triple-negative breast cancer has been previously reported." (PMID 29320557, 2018). "In addition, both raloxifene and Y134 inhibited human triple negative breast cancer (TNBC) cells by inducing apoptosis in an AhR dependent manner." (PMID 29194351, 2017). "Interestingly, many of the triple negative breast cancers cells have increased expression of AhR protein." (PMID 25068070, 2013). "In triple-negative breast cancer, suppression of either TDO or AhR was found to decrease proliferation, migration, and invasion." (PMID 41350269, 2025). "We have observed that degradation of AHR via autophagy is cell-line specific: AHR undergoes selective macroautophagy in human cervical HeLa cells and CMA in triple-negative breast cancer MDA-MB-468 cells." (PMID 37894798, 2023). "It was shown that AHR agonists TCDD and/or 3,3′-diindolylmethane and AHR inhibitors CH223191 and CB7993113 inhibited triple negative breast cancer invasion in vitro and metastasis in vivo." (PMID 33396563, 2020).
triple-negative breast carcinoma (continued). "We identified Y134 as a raloxifene analog that activates AhR-mediated transcriptional activity and induces apoptosis in MDA-MB-231 human triple negative breast cancer cells." (PMID 29194351, 2017). "Q18 triggers AHR protein degradation in triple-negative but not in non-triple-negative breast cancer cells, partly because PR-B expression blocks autophagy-dependent AHR degradation." (PMID 33562118, 2021). "In triple-negative breast cancer – characterized by lack of expression of ER, progesterone receptor (PR), and lack of human epidermal growth factor receptor 2 (HER2) overexpression – TDO is particularly elevated and drives AhR activity to promote migration, anoikis resistance, and tumor metastasis." (PMID 38807762, 2024).
cardiac hypertrophy (26 papers, 2011 to 2025). "Development of different AhR knockout mouse models in the 1990 s revealed that AhR deficiency caused cardiac hypertrophy, vascular abnormalities in multiple organs and altered blood pressure." (PMID 37696458, 2023). "AHR-deficient mice develop cardiac hypertrophy through mechanisms involving HIF-1α cell signals, Ang II-induced fibrosis, increased plasma levels of endothelin-1, and elevated mean arterial pressures." (PMID 35237156, 2022). "Benzo(e)pyrene, an isomer of BaP and a poor ligand for AhR, did not cause cardiac hypertrophy in rats, confirming the role of AhR in the development of cardiac hypertrophy." (PMID 35990352, 2022). "A recent study revealed that Vav3, an activator of Rho/Rac GTPases, regulated by AhR, was closely associated with cardiac hypertrophy and fibrosis in AhR−/− mice." (PMID 29984241, 2018). "The researchers suggested that AhR deficiency mainly lead to cardiomyocyte hypertrophy, resulting in cardiomyopathy and cardiac hypertrophy." (PMID 29984241, 2018). "It has been reported that the increased ROS level induced by the activation of the ETA receptors in the heart is associated with cardiac hypertrophy in the aryl hydrocarbon receptor null mice." (PMID 22815806, 2012). "Moreover, numerous in vivo studies have underscored the importance of AhR in normal development, linking AhR deficiency to conditions such as cardiac hypertrophy, epidermal hyperplasia, and other abnormalities." (PMID 39211042, 2024). "B(a) P was reported to cause defect of cardiovascular development by aryl hydrocarbon receptor or up regulated of rbp4 and may results in cardiac hypertrophy by activating TLR4/MyD88 signal pathway." (PMID 30112104, 2018). "However, whether the reduction in GSTM2 in heart tissues during the progression of cardiac hypertrophy and HF is related to AhR and the underlying mechanism need to be further investigated in future studies." (PMID 38037116, 2023). "This is supported by studies in AhR knockout (AhR KO) mice that exhibit cardiac hypertrophy, abnormal hepatocyte and sinusoid morphology, and vascular disorders such as failure in the developmental closure of the ductus venosus." (PMID 37686342, 2023). "This is of some importance to the role of the AhR and CYP1B1 in cardiac hypertrophy, as both kynurenine and kynurenic acid activate the AhR to increase CYP1B1." (PMID 31434333, 2019). "Knockdown of AhR results in cardiac hypertrophy and specific AhR-knock-down in vascular endothelial cells cause hypotension." (PMID 31439044, 2019). "Through a series of in vivo and in vitro experiments, they demonstrated that knockout of IDO1 and down-regulating KYN could mitigate pathological myocardial hypertrophy by modulating the expression of GATA4 (GATA binding protein 4) via AhR regulation." (PMID 38883986, 2024). "In cardiac hypertrophy models triggered by isoproterenol (ISO) and aryl hydrocarbon receptor (AhR) activation, increased CYP4A/4F enzyme expression elevates 20-HETE levels, and inhibiting its synthesis significantly mitigates hypertrophy." (PMID 39825084, 2025). "AHR expression is induced by growth factors (PDGF, FGF) and in a murine model of cardiac hypertrophy, AHR antagonizes hypoxia-induced VEGF production and the development of fibrosis." (PMID 35237156, 2022). "However, phenanthrene, which is also generally considered a poor activator of AhR-mediated CYP-1 expression, was reported to induce cardiac hypertrophy through a mechanism involving reduced miR-133 expression." (PMID 31439044, 2019). "In contrast, treatment with B[e]P, an isomer of B[a]P that is a poor AhR-ligand, did not induce cardiac hypertrophy, supporting a role of AhR in the pathogenesis of cardiac hypertrophy." (PMID 31439044, 2019).
cardiac hypertrophy (continued). "Moreover, PAHs like phenanthrene, a weak aryl hydrocarbon receptor (AHR)-mediated CYP-1 activator, have been shown to induce cardiac hypertrophy in animals through mechanisms such as decreased miR-133 expression, affecting cardiomyocytes’ size and protein content." (PMID 40137477, 2025). "Subsequent research found that cardiac function in AhR−/− mice could be completely reversed with BQ-123, an ETA receptor antagonist, indicating that ET-1 could be mediated by AhR and function as the key molecule in the progression of cardiac hypertrophy." (PMID 29984241, 2018).
Stroke (26 papers, 2016 to 2025). Sudden impairment of blood flow to a part of the brain due to occlusion or rupture of an artery to the brain. "Our results showed that post-stroke changes in the gut microbiota led to a loss of microbially-derived indole-based ligands of AHR." (PMID 37790313, 2023). "Treating with an AHR antagonist or using AHR-deficient mice resulted in a smaller infarct size and lower National Institutes of Health Stroke Scale (NIHSS) in mice model." (PMID 36032153, 2022). "Considering that the AhR antagonist 2’,4’,6-trimethoxyflavone or inhibition of kynurenine synthesis decreased stroke-associated damage, it is conceivable that the AhR plays a role in this condition." (PMID 32932962, 2020). "We observed that low stroke risk patients exhibited higher GATA-3, Foxp3, PU.1, AHR, IL-9, IL-10 and IL-22 expression levels than did patients with high stroke risk." (PMID 27115869, 2016). "This indicates that the deficiency of AhR in MG is detrimental to post-stroke functional recovery." (PMID 40963261, 2025). "Importantly, the concentrations of IAld and IPA decrease in both the plasma and the brain after stroke, indicating that stroke induces a loss of the microbiota-derived supply of indole-based ligands of AHR." (PMID 37790313, 2023). "However, AHR microbiota-derived ligands, such as indoles, are reduced in human plasma samples 24 h after ischemic stroke compared to controls, showing that post stroke GM changes could led to a loss of microbially-derived indole-based ligands of AHR." (PMID 38257864, 2023). "AhR has an important role in stroke, and its activation can aggravate ischemic injury and promote inflammatory response." (PMID 40556758, 2025). "In an experimental stroke model, the L-kynurenine/aryl hydrocarbon receptor pathway was shown to mediate brain damage after stroke." (PMID 38255299, 2024). "In this setting, the kynurenine pathway was initiated immediately after stroke and kynurenine directly contributed to the AHR activation and substantial oxidative stress, with hampered neurobehavioral performance." (PMID 39195495, 2024). "After stroke onset, activation of microglial AHR by microbial Trp-derived ligands was corroborated to suppress the expression of proinflammatory and neurotoxic genes, including TNF, IL6, IL12A, and NOS2, and boost anti-inflammatory IL10 expression." (PMID 39195495, 2024). "Despite recent advances, the role of microbiota-dependent AHR activation in regulating the post-stroke immune response remains poorly understood." (PMID 37790313, 2023). "After stroke, several immuno-regulatory pathways, including the aryl hydrocarbon receptor (AHR) pathway, become activated." (PMID 37790313, 2023). "To understand the importance of the commensal microbiota-derived ligands of AHR after stroke, we used GF animal models that are devoid of any bacteria, and thus are unable to convert Trp to indole-based molecules." (PMID 37790313, 2023). "Post-stroke treatment with IAld and IPA 3 hours post-reperfusion was associated with increased MG AHR expression." (PMID 37790313, 2023). "We hypothesize that stroke-induced dysbiosis leads to a loss of essential microbiota-derived AHR ligands and that restoring the balance between host-derived (Kyn-based) and microbiota-derived (indole-based) ligands of AHR can have therapeutic benefits after stroke." (PMID 37790313, 2023). "Plasma levels of microbiota-derived indole-based ligands of AHR were significantly reduced in samples from human stroke patients compared to controls." (PMID 37790313, 2023). "In mice, host-derived Kyn-dependent activation of AHR after stroke is detrimental, and pharmacological inhibition of AHR can be beneficial, albeit with extensive potential for adverse effects." (PMID 37790313, 2023). "Given the well-known ligand-specificity of AHR14, we evaluated the changes in host-derived and microbiota-derived ligands of AHR in the brain after stroke at multiple time points in aged WT mice." (PMID 37790313, 2023).